EZH1 (enhancer of zeste 1 polycomb repressive complex 2 subunit)
Diseases named in the same sentence as EZH1 in open-access papers (continued):
Sharing a sentence is not in itself a finding about the gene and the disease.
tumor (34 papers, 2011 to 2025). "The basis for these new developments was the detection of EZH1/2 alterations and/or EZH1/2 overexpression in many different neoplasms and their association with metastasis, poor prognosis, and treatment failure." (PMID 34944658, 2021). "In GC, the overexpression of EZH1 is associated with tumor progression and poor prognosis." (PMID 41338460, 2025). "Interestingly, EZH1 mutations were found in 27% of 123 toxic nodules, and only in tumours, which also harboured a somatic gain-of-function TSHR mutation." (PMID 32303903, 2020). "In this context, EZH1/2 inhibitors have been designed to interfere with EZH1/2 enzymes involved in histone methylation (e.g., H3K27me3), leading to tumor growth arrest or the restoration of tumor suppressor gene transcription." (PMID 33467134, 2021). "EZH1 expression was found to be strongly decreased in tumor samples (median = 5; interquartile range (IQR) = 33) compared to normal lymphoid tissue (median = 45; IQR = 65; p = 0.001)." (PMID 34944658, 2021). "It has been well-demonstrated that EZH1/2 enzymes are involved not only in tumor development and progression, but also in the regulation of normal hematopoiesis from CD34+-HSPC." (PMID 33467134, 2021). "Most strikingly, we found heterozygous loss of two tumor suppressor genes, ARID1A and SMARCE1, components of the chromatin remodeling complex SWI/SNF, and one copy gain of SUZ12 and EZH1, the components of another essential chromatin remodeling complex PRC2." (PMID 32724039, 2020). "Further, mice engrafted with shRNA-transfected cells had lower tumor weight, EZH1 downregulation in tumors and impaired rate in tumor formation." (PMID 31699991, 2019). "Given their essential functions in PRC1 and EZH1, exploring their roles in inflammation and tumor progression could open promising avenues for therapeutic development." (PMID 40042761, 2025). "Collectively, TRIM21 acts as a tumor suppressor in gastric cancer by inhibiting tumor growth, migration, and proliferation while enhancing apoptosis and chemosensitivity through the downregulation of EZH1." (PMID 39768197, 2024). "Graft anti-tumor responses can also be improved through the modulation of transcription factors and epigenetic enzymes, two widely studied methods being the knockdown of EZH1 and DNTM3A." (PMID 37064017, 2023). "Interestingly, the mean H-Score for EZH1 was significantly higher in P-NEN compared to GEP-NEN but similar for all tumor grades, while SUZ12 and EED were barely expressed across all grades and entities." (PMID 35740494, 2022). "Therefore, EZH1/EZH2 have been used to design drugs for hampering tumor growth and restoring tumor suppressor transcription." (PMID 35846880, 2022). "Finally, we took a diagram to show our work, miR-20a and UNC1999 inhibited tumor proliferation and metastasis by inhibiting EZH1." (PMID 34976797, 2021). "Four out of 10 samples showed an increase in EZH1 levels compared to those in non-tumor tissues." (PMID 34725436, 2021). "Given the crucial role of NK cells in tumor immune surveillance, in this study, we investigated whether EZH1/2 inhibitors can interfere with NK cell differentiation and functional maturation." (PMID 33467134, 2021). "Dual EZH1/EZH2 inhibition may have greater anti-tumor efficacy because EZH1 can compensate when EZH2 is inhibited." (PMID 32723346, 2020). "Our studies identified a common characteristic genetic profile of benign nodules, mutually exclusive mutation of SPOP, ZNF148 and EZH1 was observed in 24.3% of the adenomatoid nodules but not in matched PTC tumours." (PMID 28580939, 2017). "To further investigate whether this upregulation of p16INK4a was reflecting changes in the transcription levels of known regulators of this tumor suppressor, such as Bmi1 15,25, Ezh1 26, Ezh2 27,28, and Suz12 29, we analyzed the expression of these genes by qPCR." (PMID 24307508, 2014).
tumor (continued). "Up to date, there have been some approaches making CAR-T cells more persistent and enhanced anti-tumor activity in mouse tumor models, like inhibiting TCR-CD3 complex, CD155, β2-microglobulin, and EZH1, or overexpressing IL-15, IL-15R, and antigen E." (PMID 37656237, 2023). "When EZH2 is overexpressed in mature T cells with high EZH1 expression, the coexistence and function of EZH1-PRC2 and EZH2-PRC2 are phenomenally consistent with the overall increase in H3K27me3 in tumor cells." (PMID 35336993, 2022). "We demonstrated that miR-20a suppresses the tumor proliferation and metastasis in HCC by directly targeting EZH1." (PMID 34976797, 2021). "In this research, we identified that the expression of miR-20a is impaired in HCC tissues and cell lines, in a subcutaneous xenograft tumor model of HCC, due to EZH1-mediated epigenetic repression." (PMID 34976797, 2021). "EZH1/2 inhibitors impaired PRC-mediated histone methylation, leading to tumor growth arrest or restoring tumor suppressor genes transcription." (PMID 33467134, 2021). "In various cancers, targeting these genes (EZH1 and EZH2) has tumor-suppressive functions affecting tumor cell proliferation, invasion, and metastasis." (PMID 33791221, 2021). "Interestingly, Ezh2-deficient tumours assessed for H3K27me3 by immunofluorescence at endpoint exhibited undetectable levels of H3K27me3 in the tumour epithelium, indicating that Ezh1 was not able to compensate for the loss of Ezh2 histone methyltransferase activity." (PMID 29959321, 2018). "We also validate the tumor-promoting function of HOTTIP predicted to serve as miRNA sponge and positively regulate the expression of EZH1." (PMID 29041935, 2017). "In tumors, EZH1 is able to partially compensate for the function of EZH2, maintaining the methyltransferase activity of PRC2, and thereby regulating the plasticity and heterogeneity of tumor cells." (PMID 41338460, 2025). "Dual inhibition of EZH1/2 in vivo completely inhibits tumor growth without significant adverse effects." (PMID 40115023, 2025). "Although the potential relevance between EZH1 and the other three targets has not been revealed, their upregulated expression levels and pro-tumor roles have been elucidated in BC or even TNBC." (PMID 35846880, 2022). "Recently, enhancer of zeste homolog 1 (EZH1) transcriptional factor (TF), a member of the polycomb group (PcG) protein family, has been reported to participate in the proliferation and metastasis of tumor cells." (PMID 35846880, 2022). "Taken together, these results show that the combined use of EZH1/2 dual inhibitor may enhance the anti-tumor effects of sorafenib by canceling sorafenib-induced activation of EZH2 and additional inhibition of EZH1." (PMID 34725436, 2021). "In addition, EZH1 regulates the expression of EMT-related genes by maintaining specific chromatin accessibility states, thereby enhancing the invasiveness and metastatic potential of tumor cells." (PMID 41338460, 2025). "In addition, we found that the HOTTIP knockdown could inhibit the expression of EZH1 protein in the mouse xenograft tissues except for its antagonistic effect on tumor growth, which also confirmed that the mechanism of HOTTIP involved in SCLC development possibly through positively regulating EZH1." (PMID 29041935, 2017). "Similar to that of Usp22-targeted deletion, treatment of tumor cells with USP22i-S02 led to a substantial reduction in EZH2, but not EED, EZH1, and SUZ12." (PMID 41252204, 2025). "Interestingly, USP22 appears to selectively control EZH2 but not any other PCR2 complex proteins including EZH1, SUZ12, and EED in tumor cells." (PMID 41252204, 2025). "Conversely, further analysis of surviving tumor cells 48 hours after cocultivation with OT-I CD8+ T cells showed a higher USP22 and EZH2, but not EZH1 and USP27 expression, implying that the increased USP22 and EZH2 expression is involved in tumor immune evasion." (PMID 41252204, 2025).
tumor (continued). "Notably, preclinical studies have shown the concept that targeting both EZH1 and EZH2 can normalize the accumulation of H3K27me3 not only in high-grade tumor cells but also in cells in a precancerous state infected with HTLV-1 present in the peripheral blood of infected individuals." (PMID 35336993, 2022).
infection (3 papers, 2016 to 2019). The state of being infected such as from the introduction of a foreign agent such as serum, vaccine, antigenic substance or organism. "Infection of EBV mildly increased mRNA levels of EZH1 and EZH2 (2.2- and 2.1-fold, respectively)." (PMID 30487153, 2018). "HDAC5, KDM2B, EZH1, PRDM2, SETMAR, SMYD4 and USP12 were differentially expressed at all time points post-infection (excluding 2 hpi)." (PMID 30728374, 2019).
neurodevelopmental disorder (3 papers, 2023 to 2024). A behavioral and cognitive disorder with onset during the developmental period that involves impaired or aberrant development of intellectual, motor, or social functions. "In this study, we uncover recessive and dominant EZH1 variants as the cause of overlapping neurodevelopmental disorders and demonstrate an evolutionarily conserved function of EZH1 regulating neuronal differentiation." (PMID 37433783, 2023). "Here, we uncover and functionally define pathogenic variants in the chromatin modifier EZH1 as the cause of dominant and recessive neurodevelopmental disorders in 19 individuals." (PMID 37433783, 2023). "Here, the authors report that gain- and loss-of-function variants in EZH1 cause neurodevelopmental disorders, highlighting its functional relevance." (PMID 37433783, 2023). "EZH1 loss-of-function variants such as frame shift mutation or deletion mutation, and EZH1 gain-of function variants including certain missense mutations could cause neurodevelopmental disorders in human." (PMID 39072246, 2024). "Overall, our work reveals a critical role of EZH1 in neurogenesis regulation and provides molecular diagnosis for previously undefined neurodevelopmental disorders." (PMID 37433783, 2023). "In summary, these results indicate that EZH1 variants alter neurogenesis to specific cortical neuron populations which may ultimately result in defective development of neuronal networks causing the overlapping neurodevelopmental disorders associated with EZH1 LOF and GOF variants." (PMID 37433783, 2023).
bacterial infection (1 paper, 2023). "Despite the broad spectrum antiviral of Ezh1/2 inhibitors, the influence of Ezh1/2 blockage on bacterial infection needs further testing." (PMID 37239864, 2023).
cardiac disease (1 paper, 2023). "Given the partial functional redundancy between EZH1 and EZH2, additional studies into the role of EZH1 in these cardiac disease models is warranted, especially as a potential therapeutic target to offer protection following cardiac injury." (PMID 37504561, 2023).
EZH1 also shares sentences with these, for which no sentence is quoted: hepatocellular carcinoma (3 papers); melanoma (2); overgrowth syndrome (2); peripheral T cell lymphoma (2); adenoma (1); bladder cancer (1); central nervous system diseases (1); colorectal carcinoma (1); epithelioid sarcoma (1); intellectual disability syndromes (1); intellectual impairment (1); intestinal T-cell lymphomas (1); invasive breast carcinoma (1); Kabuki syndrome (1); malignant mesothelioma (1); mental disorder (1); microcephaly (1); Myelopathy (1); Neurodevelopmental delay (1); neurological disorder (1); oncocytic adenoma (1); synovial sarcoma (1); thyroid (1); triple-negative breast carcinoma (1); urogenital cancers (1); uveal melanoma (1).